EGFR (epidermal growth factor receptor)
Diseases named in the same sentence as EGFR in open-access papers (continued):
Sharing a sentence is not in itself a finding about the gene and the disease.
leukemia (97 papers, 2008 to 2025). A malignant (clonal) hematologic disorder, involving hematopoietic stem cells and characterized by the presence of primitive or atypical myeloid or lymphoid cells in the bone marrow and the blood. "Overexpression of the epidermal growth factor receptor (EGFR) is involved in cancers such as leukemia and has a downstream signaling pathway associated with the BCL-2 family." (PMID 36500355, 2022). "Their brief analysis suggests that, skin cancer and leukemia are major risk factors for using EGFR inhibitors in patients predisposed to psoriasis." (PMID 24170986, 2013). "We also re-identified midostaurin (PKC412) and lestaurtinib (CEP-701), two compounds with FL3 activity and being evaluated with leukemia, as inhibitors with direct binding affinity to EGFR T790M alleles." (PMID 24189400, 2013). "For instance, PRMT1-mediated H4R3 methylation enhances protein synthesis, promoting leukemia cell self-renewal and activating the EGFR signaling pathway." (PMID 40393971, 2025). "By this action, anti-EGFR-antibody-targeted NPs were proven to induce leukemia cell death even more successfully." (PMID 37629007, 2023). "Vascular endothelial growth factor receptor (VEGFR)) and EGFR (vascular endothelial growth factor receptor epidermal) play key roles in leukemia cell proliferation and survival." (PMID 36500355, 2022). "In leukemia, EGFR function is deregulated, playing an important role in cell survival and proliferation." (PMID 36500355, 2022). "As a result, EGFR tyrosine kinase activity is a promising therapeutic target when treating leukemia." (PMID 36500355, 2022). "The novel combination of two drug pharmacophores against the EGFR and HDACs in one single molecule was shown to have pronounced antineoplastic effects on tumor growth in both solid and leukemia/lymphoma cell models." (PMID 34445133, 2021). "Specifically, miR-146b was reported to be involved mainly in leukemia, epidermal growth factor receptor (EGFR), MAPK, and nuclear factor kappa-light-chain-enhancer of activated B cells (NF-κB) signaling pathways." (PMID 33343617, 2020). "Prolonged exposure of the conventional doxorubicin helps to escape cell death of leukemia cells, which induces drug resistance by over-expressing EGFR." (PMID 31096997, 2019). "Axl in particular has been shown to mediate the resistance of solid tumors and leukemias to epidermal growth factor receptor (EGFR)-directed chemotherapeutic agents." (PMID 25265470, 2014). "In contrast to EGFR-negative leukemia and lymphoma cells, EGFR-overexpressing cancer cells of solid tumor origin were resistant to the cytolytic activity of NKL cells." (PMID 23573299, 2013). "Considerable evidence suggests that induction of cytotoxic activity and differentiation occurs with other inhibitors of EGFR, such as gefitinib and erlotinib, in both leukemia cell lines and leukemia patients." (PMID 22216158, 2011). "While antibodies such as rituximab have proven very efficacious for the treatment of leukaemia the clinical impact of drugs such as cetuximab (anti-EGFR) and bevacizumab (anti- VEGF) in solid tumors has, however, been less dramatic." (PMID 22168338, 2011). "We have shown that EGF4KDEL's cytotoxicity is receptor specific as EGFR-/IL-4R- HPB-MLT leukaemia cells are unaffected by concentrations as high as 10 nM." (PMID 19755995, 2009). "Interestingly, we have identified the IL-15 production pathway to be activated in leukemia cells cultured in the 3D BM niche-like AML model, with different associated genes upregulated, including EGFR, IGF1R, MET, RELB, and ERBB2." (PMID 37932837, 2023). "miR-146b was upregulated in the mammary glands of the HP group, which was reported to be involved mainly in leukemia, epidermal growth factor receptor (EGFR) signaling, MAPK, and nuclear factor kappa-light-chain-enhancer of activated B cells (NF-κB) signaling pathways." (PMID 34712266, 2021).
leukemia (continued). "Likewise, in AML Syk inhibition through gefitinib suggests an EGFR independent mode of action in leukemia cells." (PMID 32404973, 2020). "Of which, EGFR, one of the transmembrane tyrosine kinase receptors, serves as a stimulus for cancer growth, which is aberrantly activated in most common tumors, including leukemia." (PMID 33109189, 2020). "The process of contact and intracellular connections and cellular migration (PLXNC1 and PCDH9 genes in leukemia) and other processes such as activating EGFR and SMAD pathways were the other processes that selected genes in this project were involved to control and regulate the processes." (PMID 29563929, 2017). "Point mutations in kinase domains of RTKs such as EGFR, HER2, MET, KIT, and FLT3 (among others) have been implicated as driver mutations in various cancers such as lung, breast, renal, liver, intestinal, and leukemia." (PMID 22347506, 2012). "Finally, although some of the EGFR signaling components are expressed in APL patient blasts, further investigations are necessary to understand their biological implications on leukemia progression, since the effects of EGFR inhibitors seem to be a result of off-target activities." (PMID 34650910, 2021). "Concurrently, Dovitinib, targeting FLT1, EGFR, FLT3 and KIT, acts as a EGFR inhibitor and FLT3 inhibitor, with previous research showing Dovitinib showed treatment efficacy in naïve and imatinib-resistant BCR::ABL(+) leukemia cells." (PMID 39247833, 2024). "Combination therapies with mAbs have been developed for non-engineered cord blood NK cells in CRC with Cetuximab (anti-EGFR mAb, NCT05040568, row 24) and with PB-NK cells in pediatric leukemia with Epratuzumab (anti-CD22 mAb, NCT00941928, row 39)." (PMID 36348457, 2022). "In addition, HR and/or c-NHEJ deficiency could be induced by the treatment of leukemia/solid tumors with the tyrosine kinase inhibitors (TKi) against the cancer-driven oncogenic tyrosine kinases (e.g., FLT3(ITD), JAK2(V617F), c-KIT(N822K), IGF-1R, EGFR)." (PMID 36497275, 2022). "Still more targets such as CLL-1, EGFR, NKG2D and mesothelin are being directed in CAR-T cell trials for leukemia and solid tumors." (PMID 31703740, 2019). "Inhibition of EGFR-MEK signaling pathway leads to the downregulation of Bcl-2 and induced myeloid leukemia cell differentiation protein Mcl-1 (Mcl-1) and promotes apoptosis to confer sensitivity to anti-EGFR treatments." (PMID 31527477, 2019). "So far all TMs described in our previous studies were directed against protein targets including CD33, CD123 in leukemias and PSCA, PSMA and EGFR in solid tumors." (PMID 29312553, 2017). "Recent research showed the ability of an insect extracts (E. sinensis Walker) to inhibit the proliferation of leukemia K562 by inhibiting EGF secreting and blocking the EGFR signaling pathway, suggesting a relevance of EGFR in human hematological diseases." (PMID 26682280, 2015). "This analysis revealed M6 subtype of acute myeloid leukemia as a cancer type in which CIP2A and representative genes of each level of the pathway (EGFR, MEK2 and ETS1) were significantly upregulated in two different genome wide leukemia studies." (PMID 21445343, 2011). "Osimertinib, a third-generation covalent EGFR inhibitor, was shown to induce the apoptosis of the CD34+ leukemia stem and progenitor cells in EGFR-negative AML and CML, but no comparable cell death occurred in CD34− cells." (PMID 39518058, 2024). "Molecular mechanism research showed that hsa_circ_0012152 played an important role in leukemia initiation and progression through miR-491-5p/epidermal growth factor receptor (EGFR)/mitogen-activated protein kinase (MAPK1) or miR-512-3p/EGFR/MAPK1 regulatory axes." (PMID 37124518, 2023). "Moreover, in EGFR-negative human leukemia K562 cells, overexpression of JMJD5 only inhibited the activation of ERK and AKT pathways after exogenous EGFR expression." (PMID 37813845, 2023).
leukemia (continued). "All in all, higher Cavin-2 may promote the resistance and progression of leukemia by regulating cell differentiation, proliferation, angiogenesis and MDR-1 or EGFR expression." (PMID 35722492, 2022). "The most common non-canonical pathway activators include, among others, the cytoplasmic non-receptor tyrosine kinases SRC and ABL (or BCR–ABL fusion proteins in Philadelphia chromosome (Ph+) leukemias), the platelet-derived growth factor receptor (PDGFR) and epidermal growth factor receptor (EGFR)." (PMID 34440253, 2021). "While, in the NALM6 as a negative-EGFR leukemia cell line, [125I]PYK binding to cell membranes was undetectable." (PMID 23494210, 2013). "Our preliminary results and other studies have shown that ErbB2 transcripts, but not EGFR transcripts, were detectable in leukemia cell lines other than K562 (data not shown)." (PMID 22216158, 2011).
COVID-19 (95 papers, 2020 to 2026). A disease caused by infection with severe acute respiratory syndrome coronavirus 2. "The most significantly associated predicted upstream regulator is EGFR, which has been implicated as a potential therapeutic target for COVID-19 treatment (33, –, 36)." (PMID 36625663, 2023). "Chronic lung injury caused by overactivity of epidermal growth factor receptor (EGFR) mediated related pathways is one of the main causes of COVID-19 induced fibrosis." (PMID 35069217, 2021). "A drug discovery study demonstrated that the anti-COVID-19 action of puerarin was associated with the suppression of oxidative stress and inflammatory cascades through the induction of EGFR." (PMID 34931923, 2021). "13.Consider adjuvant treatment with gefitinib 250 mg VO for 2 years, for elderly operated patients with a sensitivity EGFR mutation (exon 19 deletion or L858R exon 21 mutation) who have indication of adjuvant CT and higher risk of COVID-19 complications." (PMID 32578829, 2020). "The underlying mechanisms of kaempferol against COVID-19/PF co-occurrence may be related to bind to EGFR, SRC, MAPK3, MAPK1, MAPK8, AKT1, RELA and PIK3CA." (PMID 35754492, 2022). "Single-cell transcriptome analysis of monocytes from patients with COVID-19 revealed a subset with high expression of Areg and IL-18 related to pyroptosis and enriched EGFR signaling pathway, specifically present in severe sepsis cases." (PMID 40292295, 2025). "Expression levels of chorionic hormone synthesis genes such as CGB3 and EVT invasion- and differentiation-related genes such as IGFBP3 and EGFR in the second-trimester COVID-19 group were also consistent with those in the second-trimester control group." (PMID 38441496, 2024). "It is therefore unsurprising that renal failure would be more common and EGFR lower in patients with COVID-19 than in patients with pneumonia." (PMID 39266635, 2024). "Surprisingly, several research studies have pointed out that inhibition of several RTKs (e.g. epidermal growth factor receptor (EGFR), insulin-like growth factor (IGF)-1R) decreases the risk of death in COVID-19 patients." (PMID 39655133, 2024). "GDNF also interacts strongly with epidermal growth factor receptor (evidence: affinity capture-MS; green arrow) reported to regulate the severity of COVID-19 in patients." (PMID 39164284, 2024). "This analysis of real-word patient data evaluated the characteristics and the current diagnostic landscape of patients with EGFR/ALK mNSCLC across five European countries, and the impact of COVID-19 on the treatment and management of this population." (PMID 37386452, 2023). "Jing Fang Bai Du San was found to temporarily improve the clinical symptoms of patients, and network pharmacology analysis initially revealed that the targets of Jing Fang Bai Du San in the treatment of COVID-19 mainly included EGFR, PIK3CA, LCK, and MAPK1." (PMID 36782331, 2023). "Compared to patients with mild/moderate COVID-19, our CCC analysis suggested that epidermal growth factor receptor (EGFR) signaling from ciliated cells to other cell types was lost in patients with severe COVID-19." (PMID 37936693, 2023). "Overall, although the EGFR and IGF2R genes have been implicated in COVID-19, further research is required to fully comprehend their significance in the disease and to identify potential targets for treatments." (PMID 38813031, 2023). "More interestingly, our study using cancer cells reveals a possible molecular basis for COVID-19′s complications and severity observed in cancer patients by considering EGFR as a potential target for the management of such pathological and clinical situations." (PMID 37112680, 2023). "In spite of the multiple theoretical and in vitro evidences of the key role of the EGFR in COVID-19, this is the first proof of concept that blocking EGFR can have a positive impact in decreasing COVID-19 mortality." (PMID 35937253, 2022).
COVID-19 (continued). "Further, the FLT3 inhibitor gilteritinib and EGFR inhibitor abivertinib have also shown great promising potential in treating COVID-19." (PMID 36362264, 2022). "Patients & methods: The initial impact of using a drug that blocks EGFR, nimotuzumab, was evaluated in COVID-19 patients." (PMID 35306855, 2022). "According to the results of cytoscape, the targets of JFBDS for treating COVID-19 mainly contained EGFR, PIK3CA, lymphocyte-specific protein tyrosine kinase (LCK), mitogen-activated protein kinase 1 (MAPK1), MAPK3, MAPK8, STAT3, TNF, IL2 and RELA." (PMID 35165507, 2022). "This validation demonstrates the utility of targeting this pathway by EGFR/ErbB inhibitors, to achieve a downregulation of ERKs in COVID-19 treatment." (PMID 36052135, 2022). "Patients & methods: A phase I/II trial was done to evaluate the safety and preliminary effect of nimotuzumab, an anti-EGFR antibody, in COVID-19 patients." (PMID 35306855, 2022). "We identified EGFR and ErbB signaling pathways as important targets and signaling pathway of pulmonary fibrosis in patients with COVID-19." (PMID 36307516, 2022). "In conclusion, VitD can improve the pulmonary fibrosis process in COVID-19 patients through multiple targets of EGFR and MAPK and other multiple pathways." (PMID 36307516, 2022). "This clinical trial evaluated for the first time the effect of using an anti-EGFR antagonist (nimotuzumab) in combination with other drugs in the COVID-19 scenario." (PMID 35306855, 2022). "After the demonstration of EGFR expression in the lung tissue from deceased COVID-19 patients, a clinical trial using the anti-EGFR monoclonal antibody nimotuzumab was performed." (PMID 35306855, 2022). "The blockade of EGFR emerges as a novel strategy for COVID-19 patients, provided its role in inflammation, immune-thrombosis and fibrosis." (PMID 35937253, 2022). "EGFR expression was detected in the lung necropsy specimens of the 20 evaluated patients who died from COVID-19." (PMID 35306855, 2022). "In alignment with the findings in this study, the aberrant STAT pathway was found to be central to COVID-19, and the acute lung injury also activated EGFR, leading to the phosphorylation of STAT3." (PMID 36499711, 2022). "In our analysis, we identified two target gene clusters of biochanin A including inflammatory genes (IL1A, IL2, and IL6R) and cell proliferation genes (CCND1, PPARG, and EGFR) relevant to the treatment of CRC/COVID-19." (PMID 34931923, 2021). "Our results thus confirm that EGF indeed is involved in the infection processes of the lung cells and EGFR signaling is a potential drug target in COVID-19 treatment." (PMID 34045585, 2021). "We have identified gene clusters associated with CRC, COVID-19, and biochanin A. Bioinformatic analysis further showed the involvement of six core targets of biochanin A in the treatment of CRC/COVID-19, including EGFR, CCND1, IL2, IL1A, IL6R, and PPARG." (PMID 34931923, 2021). "Overall, our study provides novel insights on SARS-CoV-2 dependence on EGFR/ERK signaling and demonstrates the utility of EGFR/ErbB inhibitors for COVID-19 treatment." (PMID 34045585, 2021). "For instance, a meta-analysis showed that EGFR is involved in pathological effects on the COVID-19 inflammatory process." (PMID 34931923, 2021). "In this context, EGFR, a known target of miR-27b-3p, miR-146a-5p, miR-16-5p, miR-335-5p and miR-30a-5p, is found at higher levels in patients with COVID-19, likely enhancing these events." (PMID 35087533, 2021). "As a next step towards understanding the mechanisms of EGFR-signaling implementation in the COVID-19-related severity, we stimulated A549 and H1299 cells with the recombinant EGF before the addition of lentiviral particles." (PMID 34045585, 2021). "Using the network pharmacology approach, we identified two clusters of genes involved in immune response (IL1A, IL2, and IL6R) and cell proliferation (CCND1, PPARG, and EGFR) mediated by biochanin A in CRC/COVID-19 condition." (PMID 34931923, 2021).